NF1 (neurofibromin 1)
Diseases named in the same sentence as NF1 in open-access papers (continued):
Sharing a sentence is not in itself a finding about the gene and the disease.
melanoma (continued). "Although the mechanism is not elucidated in GC, loss of NF1 has been associated with resistance to EGFR TKIs in lung adenocarcinomas and resistance to BRAF inhibitor in melanoma by increasing MAPK and/or PI3K signaling via negatively regulating Ras." (PMID 34399705, 2021). "A major impediment to the development of targeted therapies for patients with NF1-mutant melanomas has been the lack of suitable animal models." (PMID 34331013, 2021). "Of the 28 melanoma cell lines, 22 harbored BRAF V600 mutations, 4 harbored oncogenic NRAS mutations, one was NF1‐mutant (in the absence of BRAF or NRAS mutations), and the remainingline was triple‐wild‐type." (PMID 32767816, 2021). "One study found that the loss of NF1, which frequently co-occurs with RAS alterations in melanoma, is associated with loss of negative feedback to RAS activation, resulting in increased activation of RAS and downstream resistance to RAF inhibition." (PMID 33807778, 2021). "In a phase 1 study using trametinib in advanced melanomas, trametinib did not demonstrate efficacy in the majority of patients with BRAF/NRAS wild-types, but one patient with an NF1 mutation had a stable disease." (PMID 34831002, 2021). "In order to track the melanoma cells using EGFP instead of melanin, we bred the sox10:EGFP fluorescent zebrafish line into our nf1/pten-mutant line to aid in visualization of the transplanted melanoma cells, as they expressed high levels of the neural crest progenitor marker sox10." (PMID 34331013, 2021). "Using genome-scale analyses, melanoma has been classified into four distinct groups based on their NRAS, BRAF, and NF1 status: NRAS-mutant, BRAF-mutant, NF1-mutant, and triple-negative (NRAS/BRAF/NF1 mutant) melanoma." (PMID 33766731, 2021). "Triple wild-type melanomas (BRAF, RAS, and NF1 wild type) typically lack a UV signature." (PMID 32123303, 2020). "The systematic evaluation of over 500 melanoma genomes in the last decade has identified a series of frequently and significantly altered oncogenes and tumor suppressor genes, including BRAF, NRAS, RAC1, NF1, CDKN2A, PTEN, and ARID2." (PMID 33076392, 2020). "Non-CSD melanomas are often associated with BRAFV600E mutations that are found in common nevi as well, while CSD melanomas are often seen to have NF1, NRAS, or BRAFnonV600E mutations." (PMID 33339193, 2020). "Other genetic drivers in the pathogenesis of melanoma include NRAS and neurofibromatosis 1 (NF1) mutations, but these will not be discussed in detail in this article." (PMID 32645969, 2020). "Currently, there’s no clinical trial investigating NF-1 mutant melanoma, while a combination of MEK and PI3K or mTOR inhibitors showed promising activity in mouse models." (PMID 33233603, 2020). "The hyperactivation of the RAS/RAF/MEK/ERK signaling pathway (hereafter MAPK), which is assessed in the vast majority of melanomas as a result of genetic alterations in BRAF, RAS, or NF1 among others, contributes to the pro-survival phenotype of melanoma cells." (PMID 32340261, 2020). "These driver mutations are almost always mutually exclusive, making it possible to classify melanoma cases in distinct genomic subtypes: BRAF, RAS, NF1, and Triple-WT, the latter being defined by the absence of BRAF, RAS, and NF1 mutations." (PMID 30166456, 2018). "In particular, we hypothesized that inhibition of MEK and upregulation of NF1 levels, by CAPN1 inhibition, might have a synergistic effect on melanoma cells." (PMID 30131853, 2018). "Given that Calpain inhibitor I expression leads to increased NF1 stability and RAS inhibition and the strong contribution of the RAS pathway to promoting tumorigenesis, we reasoned that NF1 and CAPN1 expression levels may affect melanoma patient survival." (PMID 30131853, 2018).
melanoma (continued). "This novel mechanism for regulating NF1 in melanoma provides a molecular basis for targeting CAPN1 in order to stabilize NF1 levels and, in doing so, suppressing Ras activation; this mechanism can be exploited therapeutically in melanoma and other cancers." (PMID 30131853, 2018). "Taken into consideration that both NF1 and RAS alterations can additionally activate PI3K signaling, this pathway could be of particular significance in mucosal melanomas." (PMID 28380455, 2017). "The impact on NRAS is however non-uniform, with some NF1 mutant melanomas exhibiting full NRAS activation (i.e. the same activation level as oncogenic NRAS mutations), whereas others exhibit only partial activation." (PMID 28637487, 2017). "CJM, HMCB, and CHL1 also lacked mutations in BRAF, NRAS, or NF1, but these cell lines had similar FGA and mutational burden relative to other melanoma cell lines as well as tumors." (PMID 29383127, 2017). "Before analyzing these various gene expression-based classifications, it is important to point out that these classifications are not overlapping with the TCGA molecular classification of melanomas based on the mutational status for BRAF, NRAS, and NF1." (PMID 29156643, 2017). "NF1-null melanoma cell line, MeWo, but not wild-type NF1 carrying cell line 92.1, showed similar decrease in active Ras in response to CB-839 treatment." (PMID 29212209, 2017). "The analysis of mutated genes showed remarkable differences between these three subtypes of melanomas: most acral and mucosal melanomas (51%), but only 11% of cutaneous melanomas lacked BRAF, NRAS, or NF1 mutations." (PMID 29156643, 2017). "Similar decrease in cell viability, induction of PARP and downregulation of downstream signaling pathways was observed for the NF1-null melanoma cell line, MeWo but not for the wild-type NF1 carrying melanoma cell line, 92.1." (PMID 29212209, 2017). "In this study, we found that the EPE peptide also reduces the viability of NRAS and some NF1 mutant melanomas as well, and combination of EPE peptide and MEK inhibitor trametinib showed synergy in reducing the growth of other melanomas, including those resistant to each drug alone." (PMID 29180761, 2017). "In summary, we have demonstrated that the combination of GSI-I with ABT-737 killed the bulk and the MICs of multiple melanoma samples, irrespective of the mutational status of BRAF, NRAS or NF-1." (PMID 27829238, 2016). "Another major drawback of current melanoma treatments is the lack of therapeutic options for patients who are WT for common mutations in BRAF, NRAS or NF-1 (Triple-WT)." (PMID 27829238, 2016). "While NF1 shows higher activity toward K- and H-, but not N-Ras in melanoma, RASA1 has increased activity toward R-Ras compared with H-Ras." (PMID 26993606, 2016). "We and others have shown that inactivation of the NF1 gene in human neuroblastoma and melanoma cell lines does not result in increased levels of the GTP-bound form of Ras compared to similar lines that express normal levels of the NF1 protein." (PMID 27130733, 2016). "Alterations in the tumor suppressor NF1, a negative effector of Ras, were present in a thin melanoma (M16, non-sense mutation and copy loss) harboring wt BRAF and in a thick melanoma (M9, non-sense mutation) with BRAF V600E." (PMID 27095580, 2016). "Tumor suppressive function of NF1 (neurofibromatosis type 1) in several cancer types including melanoma, DAB2IP in prostate cancer, RASAL2 in breast cancer, PLXNC1 (Plexin C1) and RASA2 in melanoma have been described." (PMID 26993606, 2016). "The BRAF/NRAS wild-type melanomas, i.e. samples negative for mutations in both BRAF and NRAS, more often had genetic alterations in KIT or NF1 (P < 0.001, Fisher's exact test)." (PMID 25909218, 2015). "We selected melanoma cell lines (MM253 and MM96L) that had detectable NF1 protein to assess if NF1 expression could be altered following manipulation of miR-514a." (PMID 25980496, 2015).
melanoma (continued). "There are no specific treatment options for NF1- disrupted tumors, but in recent studies of NF1 in melanoma, it was successfully targeted in mouse models with a combination of MEK and PI3K/mTOR inhibitors." (PMID 24722523, 2014). "Despite the molecular findings supporting a melanoma promoting genetic background in the analyzed NF1 case, the question remains why melanoma incidence is not markedly elevated in NF1." (PMID 16961930, 2006). "Although melanocytes derive from neural crest cells as well, melanoma incidence does not seem to be markedly elevated in NF1." (PMID 16961930, 2006). "The rarity of this association given the frequency of NF-1 (1 in 3000) suggests that the probability of NF-1 patients developing malignant melanoma is no more than the general population." (PMID 15363097, 2004). "Since no more than 100 cases of melanoma (all sites combined) developing in NF-1 patients have been reported, the incidence is significantly lesser than the 1.5% that can be attributed to chance alone." (PMID 15363097, 2004). "NF1 gene mutations, leading to the abrogation of negative regulatory pathways in RAS-associated MAPK pathways, exhibit a substantial mutation prevalence of 12-18% in melanoma patients." (PMID 41142596, 2025). "However, the absence of melanoma markers, including HMB45 and Melan-A, and the negative molecular profile for any melanoma-associated genetic alterations, including BRAF, NRAS, and NF1 gene alterations, argued against such an entity." (PMID 40978976, 2025). "However, features relating SVs across histologic subtypes, or genomic (BRAF-, (N)RAS-, and NF1-mutant and triple-wild-type [TWT]) subtypes of melanoma (which have been shown to have distinct secondary driver genes and pathways), remain incompletely characterized." (PMID 38758740, 2024). "Clinical trials are not currently explicitly conducted for patients with NF1 mutant melanomas." (PMID 38534309, 2024). "Moreover, genes KDM5D, UTY, and NF1 have demonstrated gender differences in lung cancer, while PPP6C and IGF1R exhibit sex-biased expression in melanoma, and the NRAS gene may play sex-specific roles in acute myelogenous leukemia." (PMID 39541191, 2024). "Unlike melanoma, which is a malignant tumor, NF1 is a benign tumor in nature, and therefore the difference in RP2D may be due to differences in the two patient populations, resulting in different tolerance." (PMID 37400844, 2023). "Furthermore, AR was found significantly associated with OS in RAS mutant subtypes of melanoma but not in BRAF, NF1, or triple-wild type subtypes of melanoma." (PMID 36833272, 2023). "Specifically, M1 cells exhibit a neural crest–like phenotype and cluster with BRAF-mutant human melanomas, M4 cells have a transitory phenotype and cluster with RAS-mutant human melanomas, and M3 cells have a melanocytic phenotype and cluster with human triple-WT (BRAF/RAS/NF1-WT)." (PMID 37471141, 2023). "In comparison to other neoplasms, patients with NF1 had considerably lower disease-specific survival (DSS) rates if they developed undifferentiated pleomorphic sarcoma (UPS), high- grade glioma (HGG), malignant peripheral nerve tumor (MPNST), ovarian cancer, or melanoma." (PMID 36090331, 2022). "Interestingly, rearrangements and amplification of the MAP3K8 gene leading to increased levels of the truncated, active form of this protein are detected in approximately 15% of melanomas without driver mutations, such as BRAF, NRAS, or NF1." (PMID 35565444, 2022). "Melanomas were enriched in “naive T-cell”, “effector memory T-cell”, “exhausted T-cell”, “resting Treg T-cell” and “Th1-like” signatures, irrespective of their BRAF, NF1 or RAS mutational status." (PMID 36389735, 2022).
melanoma (continued). "Finally NF1 mutations are associated with high-CSD CMs, while the triple-negative type is usually present in very low or non-CSD melanomas." (PMID 36143375, 2022). "Additionally, a triple wild-type melanoma has been described, being characterized by the lack of BRAF, RAS (N/H/K), and NF1 mutations." (PMID 35334544, 2022). "However, in our study, none of the cases were found to harbor NF1 and PDGFRA mutations in melanomas of the female genital tract, as well as in cutaneous melanomas, acral melanomas and melanomas of nasal cavity." (PMID 34102999, 2021). "Hence, similar to the NF1-mutant class of human cutaneous melanomas, the loss of nf1 is sufficient to provide RAS pathway activation, and zebrafish melanomas in this background do not contain braf/nras hot-spot mutations." (PMID 34331013, 2021). "To date, no studies have identified an effective targeted therapy in NF1 mutant melanomas." (PMID 34831002, 2021). "Notably, none of the cases were found to harbor SF3B1, NF1, KIT and PDGFRA mutations in cutaneous melanomas, acral melanomas and melanomas of nasal cavity." (PMID 34102999, 2021). "According to the data published by the TCGA network based on whole exome sequence analysis of patients with primary and/or metastatic melanoma, melanoma could be classified into four genomic subtypes: mutant BRAF, mutant RAS, mutant NF1, and Triple-WT (wild-type)." (PMID 34035810, 2021). "Non-CSD-associated melanomas encompass acral and mucosal melanomas that usually do not show BRAF, NRAS, or NF1 mutations (triple wild-type), but in a subset may have KIT or SF3B1 mutations." (PMID 34571969, 2021). "Notably, genomic landscape of triple wild-type melanomas (lacking mutations in RAS, RAF and NF1 genes), which account for 5–10% of melanomas, was recently characterized as being enriched for mutations in DNA repair-related genes." (PMID 33800547, 2021). "Interestingly, these differential expressions were independent of the status of key melanoma mutations including BRAF, NF1, RAS mutations and triple wild type using GEPIA database." (PMID 34809598, 2021). "We analyzed a few of the top DEGs (NRP2, CAPN3, DMBT1, BRAF, DDIT3, PPP1R3C, NF1) using The UCSC Xena platform that has large number of RNA-seq data of normal tissue from healthy individuals (GTEx) and primary tumor and metastatic tissue data from melanoma patients (TCGA)." (PMID 32983966, 2020). "NF1 and Triple-WT subgroups were unbiased between melanomas arising in non-CSD and acral skin." (PMID 32083130, 2020). "This is especially true for patients who show no benefit after standard of care, become resistant or belong to somatic mutation subgroups for which no targeted therapy option exists, such as BRAF wild-type melanomas including NRAS mutant and NF1 loss-of-function melanomas." (PMID 33260923, 2020). "Although, we did not identify any melanoma cell lines with PIK3CA activating mutations in the GDSC database, these data indicate that activating RAS mutations and loss-of-function NF1 or PTEN mutations do not diminish the sensitivity of melanoma cell lines to MEK inhibition in vitro." (PMID 30237495, 2018). "Thanks to the recent advances in deep sequencing, melanomas are now classified at the molecular level depending on the mutational status of their major oncogenic drivers (BRAF, NRAS, and NF1), and are considered as “triple-negative” when no mutations are present in these genes." (PMID 29534457, 2018). "Similarly, loss of function mutations in the negative PI3K regulators, NF1 and PTEN or activating NRAS mutations, did not significantly reduce the sensitivity of BRAFV600E-mutant melanoma cells to trametinib." (PMID 30237495, 2018). "The genomic landscape of melanoma, performed by The Cancer Genome Atlas (TCGA) on 333 melanoma samples delineated 4 genomic subtypes, i.e., triple wild-type (WT), BRAF mutant, NRAS, HRAS or KRAS mutant, and NF1 mutant, as well as three transcriptomic subclasses, i.e., immune, keratin and MIFT-low." (PMID 29743104, 2018).
melanoma (continued). "However, the binding partners of NF1 and the pathways in which it is involved in melanoma have not been characterized in an in depth manner." (PMID 30131853, 2018). "Therefore it seems that there might be some patients with NF1mt melanoma suitable for MEK inhibitor treatment, although further studies are necessary to elucidate the role of NF1." (PMID 28350340, 2017). "However, Krauthammer and colleagues showed that not all NF1 mutated melanoma were responsive to MEK inhibition and that many NF1 mutated melanoma had concurrent mutations in RAS related genes." (PMID 28350340, 2017). "On the one hand, melanomas with chronic sun-induced damage (CSD) harbor mutations in KIT proto-oncogene receptor tyrosine kinase (KIT, Gene ID: 3815), NF1, NRAS, and BRAF but typically not BRAF(V600E), the specific BRAF mutation that commonly arises in atypical melanocytic neoplasms." (PMID 28265786, 2017). "The capacity of NF1 mutations to act both cooperatively and exclusively without BRAF and NRAS mutations in melanoma may be mediated through pathways other than the MAPK pathway." (PMID 28637487, 2017). "NF1 suppression can lead to increased RAS activation in melanoma, which may explain the lack of correlation between ERK phosphorylation and BRAF mutational status." (PMID 28938534, 2017). "To address the limitations of melanoma therapies, we included multiple tumor samples of patients relapsed from current treatments, with a diverse genetic background (with or without the common BRAF, NRAS or NF1 mutations) in these studies." (PMID 27829238, 2016). "NF1-mutant melanomas are unlikely to respond to standard BRAF-targeted therapies but may benefit from drugs targeting the MEK and PI3K pathway instead." (PMID 25026295, 2014). "Assuming that neurofibromin does not control proliferation of mature skin melanocytes or putative melanocyte stem cells, one may not expect that the NF1 genetic background enhances melanoma development from these cells." (PMID 16961930, 2006). "The existence of distinct and divergent tumor evolution pathways in malignant melanoma may serve as a complementary explanation for the apparent lack of a grossly elevated melanoma incidence in NF1." (PMID 16961930, 2006). "NF1-mutant melanomas were significantly associated with non-duplication SV events in two RASopathy genes, RAF1 and SPRED1 (Fisher’s exact, OR = 5.03, 95% CI = 1.46–16.42, P = 4.8 × 10–3), the latter of which has also been identified as a significantly mutated gene exclusive to NF1-mutant melanomas." (PMID 38758740, 2024). "For the 45 patients with resected melanoma brain metastases undergoing targeted DNA sequencing, molecular classification recapitulated The Cancer Genome Atlas groups (NRAS variant, BRAF variant, NF1 variant, and triple wildtype) with no subtype enrichment within the brain metastasis cohort." (PMID 37589977, 2023). "Cutaneous melanomas are classified into four subtypes: (i) mutation of the B-Raf proto-oncogene serine/threonine kinase (BRAFmut), (ii) mutation of the NRAS proto-oncogene GTPase (NRASmut), (iii) mutation of neurofibromin 1 (NF1mut), and (iv) none of the three, triple BRAF/NRAS/NF1 wild-type (WT)." (PMID 36428530, 2022). "Additionally, the loss of NF1 can result in RAS resistance to negative feedback, and NF1 inactivation in melanoma harboring BRAF mutation results in a selective advantage by reversing oncogene-mediated suppression of RAS, which is driven by ERK-induced negative feedback." (PMID 36181568, 2022). "Therefore, melanomas may be molecularly classified into four major genetic subtypes: BRAF-mutated, RAS-mutated, NF1-mutated and, if none of the three previous genes are mutated, triple-wildtype." (PMID 36143375, 2022).